INS (insulin)
Diseases named in the same sentence as INS in open-access papers (continued):
Sharing a sentence is not in itself a finding about the gene and the disease.
type 2 diabetes (continued). "The progression from glucose intolerance to type 2 diabetes is finely related with insulin secretory dysfunction and significant loss of functional beta-cells." (PMID 23737653, 2013). "Patients with type 2 diabetes exposed to sulfonylureas and exogenous insulin had a significantly increased risk of cancer-related mortality compared with patients exposed to metformin." (PMID 23415113, 2013). "Type II diabetes is the most common type counting about 90-95% of the diagnosed cases, characterized with normal or even excess of insulin levels with insulin resistance being the major cause of increased glucose levels." (PMID 23351604, 2013). "Studies have shown that magnesium can improve insulin sensitivity by acting as a mild calcium antagonist and reduce the risk of type 2 diabetes." (PMID 23434909, 2013). "Progression of type 2 diabetes is characterised by loss of early insulin secretion, leading to postprandial hyperglycaemia." (PMID 23691521, 2013). "This review will explore the current evidence underlying this concept of meal-driven insulin intensification for the treatment of Type 2 diabetes, as well as the implications of adopting such an approach in clinical practice." (PMID 22998363, 2013). "A current study also found that physical exercise can control, prevent, or delay the onset of type 2 diabetes by markedly improving the low insulin sensitivity in at-risk patients." (PMID 24282635, 2013). "Metformin improves insulin sensitivity, lowers blood glucose and cholesterol, and reduces body weight in some individuals with type 2 diabetes, although the underlying mechanisms of action, which include modulating AMPK activation, remain poorly understood." (PMID 24209692, 2013). "Genome-wide association studies (GWASs) have discovered association of several loci with Type 2 diabetes (T2D), a common complex disease characterized by impaired insulin secretion by pancreatic β cells and insulin signaling in target tissues." (PMID 23308243, 2013). "The study demonstrated that NEAT is associated with amelioration in insulin sensitivity, waist circumference, high-density lipoprotein-cholesterol, blood pressure and the marker for atherosclerosis in patients with type 2 diabetes." (PMID 23711224, 2013). "The effect of BMP4 variants on type 2 diabetes which is definitely through impact on impaired insulin secretion or insulin sensitivity is rather ambiguous." (PMID 24350253, 2013). "A recent observational study showed that the rapid-acting insulin analog gluslisine was associated with a reduced incidence of macro- and microvascular events in patients with type 2 diabetes in comparison with human regular insulin." (PMID 24244557, 2013). "We did indeed find directionally consistent enrichment (binomial P<0.05) for women-specific associations (P-women<0.05) with lipids, fasting insulin, type 2 diabetes, and HOMA-B (binomial P from 1.2×10−5 to 5.9×10−3)." (PMID 23754948, 2013). "Insulin signaling in the brain plays an important role in the regulation of peripheral fat and glucose metabolism, and deficits in brain insulin signaling have been linked to development of diabetes type 2 (DT2) and obesity." (PMID 23915208, 2013). "This is the first in vivo biochemical study in humans to provide evidence that the vasodilatory effects of insulin are associated with activation of the L-arginine-NO pathway and this appears to be impaired in type 2 diabetes." (PMID 23658699, 2013). "Functional common SNPs of genes included in the insulin signalling pathway influence IR and the susceptibility to type 2 diabetes." (PMID 23394097, 2013). "An existing toolbox of well-tolerated insulin-lowering therapies has accumulated over several decades to treat type 2 diabetes and metabolic complications associated with obesity." (PMID 23573093, 2013). "VLDL overproduction and the loss of insulin suppression of apoB secretion occur in patients with type 2 diabetes." (PMID 23617853, 2013).
type 2 diabetes (continued). "Thirdly, the state of the art metabolic assessment techniques, including body composition analysis and insulin sensitivity testing, allows for comprehensive and developmentally appropriate assessment of early cardiovascular disease and type 2 diabetes risk." (PMID 23947389, 2013). "Significance: Insights into the biochemical basis of glucose-stimulated insulin secretion are critical for understanding root causes of type 2 diabetes." (PMID 23426361, 2013). "This suggests a minimum prevalence of absolute insulin deficiency in insulin‐treated Type 2 diabetes of 3% [5/186, excluding the five subjects who were unable to provide repeat urine samples or participate in the MMTT]." (PMID 23659458, 2013). "Several recent studies have suggested that in insulin-naïve people with type 2 diabetes, higher levels of depression are associated with a more negative appraisal of insulin therapy." (PMID 24223860, 2013). "Excess fructose consumption is closely associated with the development of type 2 diabetes due to insulin insensitivity and dyslipidemia." (PMID 23590862, 2013). "Type 2 diabetes (T2D) is characterized by tissue insulin resistance combined with a relative deficiency in insulin secretion." (PMID 23576986, 2013). "The aim was to investigate the association between human insulin and cancer incidence and mortality in Chinese patients with type 2 diabetes." (PMID 23308218, 2013). "This gene is a zinc transporter related to SLC30A8, which has been implicated in type 2 diabetes, and zinc transport plays a role in insulin secretion by pancreatic -cells." (PMID 23825936, 2013). "Variations in CDKAL1 have been reported to be associated with impaired insulin secretion and the increased risk of type 2 diabetes." (PMID 23990951, 2013). "At low dose, STZ (50 mg/kg b.w) partially destructs the beta cells resulting in insufficient insulin secretion causing type 2 diabetes." (PMID 23414307, 2013). "Another possibility is the loss of normal pulsatility of insulin secretion, which occurs in type 2 diabetes, although the underlying mechanisms controlling this are poorly understood." (PMID 23613779, 2013). "Impaired insulin homeostasis or glucose tolerance with HFFD is an important predictor of type 2 diabetes, which was reflected by increased risk factors, including HbA1c and HOMA-IR." (PMID 23690866, 2013). "Many researchers agree that Type II diabetes is predominantly caused by impairment of the insulin-signalling pathway, even though the exact disease pathogenesis is yet to be understood." (PMID 24324517, 2013). "Obesity is a key risk factor for type 2 diabetes as it desensitizes glucose recipient organs to the action of insulin." (PMID 23542897, 2013). "Chronic elevation in plasma NEFA level is commonly associated with impaired insulin-mediated glucose uptake and often coexists with obesity and type 2 diabetes." (PMID 23876229, 2013). "Nonetheless, it is recognized that those pregnant women who require insulin to maintain the target glucose values are at a true risk of suffering type II diabetes and experiencing cardiovascular complications later in life." (PMID 23324111, 2013). "Type 2 diabetes is associated with overweight and obesity and has a complex pathophysiology characterized by abnormalities in insulin secretion, excess hepatic glucose production and insulin resistance in the liver and peripheral target tissues." (PMID 23061470, 2013). "In type 2 diabetes, the reduction in beta-cell function is associated with the loss of glucose-stimulated insulin secretion (GSIS) and the reduction of beta-cell mass." (PMID 23737653, 2013). "hIAPP fibrillization implicated in Type 2 diabetes pathology involves formation of oligomers toxic to insulin producing pancreatic β-cells." (PMID 23435449, 2013). "Type 2 diabetes mellitus is associated with decreased insulin sensitivity in liver and skeletal muscle." (PMID 23341947, 2013).
type 2 diabetes (continued). "Exercise also reduces the likelihood of developing type 2 diabetes—a major risk factor for stroke—by increasing the body's sensitivity to insulin." (PMID 24059905, 2013). "Well-controlled laboratory studies also provide credible evidence that sleep loss impairs glucose clearance and insulin sensitivity, increasing type 2 diabetes risk." (PMID 24282622, 2013). "Palmitoleic acid is associated with increased insulin concentrations and resistance, type II diabetes, metabolic syndrome, heart failure and coronary heart disease." (PMID 23614006, 2013). "In the islet cells of type 2 diabetes patients, Human Islet Amyloid Polypeptide (hIAPP) causes β cell loss and low insulin secretion; zinc significantly inhibits hIAPP amyloid fibrillogenesis and has been shown to prevent hIAPP mediated β cell loss." (PMID 23613929, 2013). "The insights of the last decade into the genetics of type 2 diabetes and impaired glucose and insulin metabolism have yielded dozens of replicated risk loci." (PMID 24322525, 2013). "Potassium voltage-gated channel, KQT-like subfamily, member 1 (Kcnq1) is a type 2 diabetes susceptibility gene implicated in reduced beta cell function and decreased insulin secretion." (PMID 23542897, 2013). "Another target, Tcf7l2, is also involved in insulin secretion and genetic variation in this gene is a risk factor for type 2 diabetes." (PMID 24109547, 2013). "One found that waist circumference and BMI were more strongly correlated than BAI with OGTT-derived insulin sensitivity and type 2 diabetes risk." (PMID 23776578, 2013). "Common variants in the KCNQ1 gene are associated with type 2 diabetes in a Dutch population, which can be explained at least in part by an effect on insulin secretion." (PMID 22403629, 2012). "Numerous clinical trials have indicated that ACE inhibitors and angiotensin receptor blockers (ARBs) decrease the propensity to develop type 2 diabetes in high-risk patients, likely due to insulin sensitivity improvement." (PMID 22804097, 2012). "Adiponectin is an obesity related protein that mediates the risk of type 2 diabetes in obese individuals with its anti-inflammatory and insulin-sensitizing properties." (PMID 23396303, 2012). "It has been demonstrated that increased GPT and CRP plasma levels are associated with decreased hepatic insulin sensitivity, insulin resistance and an increased risk for the onset of MS and type 2 diabetes." (PMID 22611357, 2012). "Islet vascularization, by controlling beta-cell mass expansion in response to increased insulin demand, is implicated in the progression to glucose intolerance and type 2 diabetes." (PMID 22272235, 2012). "Intravenous administration of the incretin hormones in patients suffering from type 2 diabetes causes the increase in early-phase insulin secretion in response to a meal, but only GLP-1 is able to stimulate insulin secretion in late phase." (PMID 22462016, 2012). "In conclusion, we have shown that a simple, inexpensive, well tolerated, non-pharmacological dietary supplementation with HAM-RS2 can improve first-phase insulin secretion in overweight individuals who are at increased risk of developing type 2 diabetes." (PMID 22815837, 2012). "This study showed that just four weeks of resistant starch intake significantly increased the first-phase insulin secretion in individuals at risk of developing type 2 diabetes." (PMID 22815837, 2012). "Type 2 diabetes is associated with a gradual loss of insulin secretion and a progressive reduction in β-cell mass." (PMID 22518128, 2012). "Loss of first-phase insulin secretion is a well-characterised defect in type 2 diabetes and improvement in this following a simple dietary intervention has potentially important clinical implications." (PMID 22815837, 2012). "As one concrete example, maternal alleles associated with type 2 diabetes influence the BW of offspring in part by influencing maternal fasting glucose and insulin levels during pregnancy." (PMID 22848409, 2012).
type 2 diabetes (continued). "Type 2 diabetes and insulin use in the diabetic patients are significantly associated with a higher incidence of HP eradication." (PMID 22571603, 2012). "This profile mimics the progressive loss of glucose-stimulated insulin secretion in human type 2 diabetes (T2DM) and therefore the ZDF rat represents a good animal model for studying human T2DM pathophysiology and the effects of therapeutic options." (PMID 23201769, 2012). "In the present study we demonstrate that exposure to low doses of BPA during adulthood promotes adverse effects on glucose homeostasis and insulin action on peripheral tissues with the concomitant risk of developing type 2 diabetes." (PMID 22470480, 2012). "Type 2 diabetes is characterized by loss of first phase and impaired second phase insulin release with disappearance of the regular pulsatile secretory pattern." (PMID 22970724, 2012). "Type 2 diabetes is caused by complex interactions between insulin resistance in the peripheral tissues and impaired insulin secretion by pancreatic β-cells." (PMID 22518128, 2012). "Our findings in this report are contradictory to some suggestions regarding possible risk factors for type 2 diabetes that modulate insulin sensitivity." (PMID 22698081, 2012). "Down-regulation of SREBP-1c was observed in the adipose tissue of leptin deficient mice (ob/ob), in insulin-resistant humans during fasting and in response to insulin, and in adipose tissue of patients with type 2 diabetes, similar to our study." (PMID 22471940, 2012). "T1D is caused by a relative or absolute deficiency of insulin secretion, but type 2 diabetes is mainly characterized as an insulin resistance state." (PMID 22973238, 2012). "We examined the association of these variants within KCNQ1 with type 2 diabetes in a Dutch population, investigated their effects on insulin secretion and metabolic traits and on the risk of developing complications in type 2 diabetes patients." (PMID 22403629, 2012). "Common variants at this locus have been associated with type 2 diabetes, fasting glucose and pro-insulin level, and it is suggested that this effect is mediated through reduced insulin secretion capacity." (PMID 22662265, 2012). "Recently, Prkce has been implicated in the loss of insulin secretory responsiveness during the development of type 2 diabetes, while others highlighted its role in the pathomechanism of drug dependence and addiction." (PMID 22369239, 2012). "In a significant portion of Type 2 diabetic patients, the disease progresses to a complete loss of β-cell insulin secretion, thus necessitating exogenous administration of insulin, in addition to other medications, to achieve adequate glycemic control." (PMID 22761194, 2012). "The saturated fat intake reduction improves insulin sensitivity, independently of the energy intake; however, a sustained high protein intake is associated with increased incidence of type 2 diabetes and diabetic nephropathy." (PMID 23097695, 2012). "While the hGLUT4 transgenic (hGLUT4 TG) mice are highly insulin sensitive, they develop metabolic characteristics that are highly linked to type 2 diabetes in humans, including hepatic steatosis and obesity." (PMID 27335671, 2012). "An increase of these enzyme activities is also associated with fatty liver disease and decreased hepatic insulin sensitivity in type-2 diabetes." (PMID 23304131, 2012). "In conclusion, we here show that common variation in the KCNQ1 gene affect second-phase insulin secretion and confirm the association of the gene with type 2 diabetes in a Dutch population." (PMID 22403629, 2012). "Type 2 diabetes is a chronic metabolic disease that can be caused by pancreas β-cell dysfunction, deficiency in insulin secretion, insulin resistance and/or increased hepatic glucose production." (PMID 23554750, 2012).
type 2 diabetes (continued). "Systemic SP-D was recently demonstrated to be decreased in type II diabetes, positively associated with insulin sensitivity after oral glucose tolerance test and negatively associated with obesity." (PMID 22509382, 2012). "The excess of adiposity is an established risk factor for the development of cardiovascular diseases, type 2 diabetes, and hypertension, all characterized by resistance to insulin-mediated glucose disposal." (PMID 22701480, 2012). "In observational surveys on type 2 diabetes, insulin therapy is associated with an increased incidence of several forms of cancer, although it is difficult to discriminate the effect of confounders from that of insulin itself." (PMID 23209929, 2012). "Type 2 diabetes is a risk factor for Alzheimer's disease (AD), most likely linked to an impairment of insulin signalling in the brain." (PMID 22443187, 2012). "Animal studies have shown that loss of Cx36 is associated with the loss of pulsatile insulin release, increase in basal insulin output, and reduced glucose-induced insulin release (these secretory defects are similar to those observed in type II diabetes)." (PMID 22536530, 2012). "A hallmark of the onset of type 2 diabetes is a progressive decrease in insulin-stimulated glucose uptake." (PMID 22675354, 2012). "Type 1 diabetes is characterized by absolute deficiency of insulin secretion resulting from autoimmune response targeting the β-cells of the pancreas; type 2 diabetes is triggered by a combination of resistance to insulin and insufficient β-cell function." (PMID 24278682, 2012). "A still increasing number of common genetic variants associated with type 2 diabetes or associated with type 2 diabetes related phenotypes like fasting glucose, fasting insulin or 2-h glucose have been identified.." (PMID 23185617, 2012). "Hybrid-R has been shown to be abundantly expressed in adipose tissue and skeletal muscle of type 2 diabetic patients, and is associated with lower insulin sensitivity." (PMID 22879999, 2012). "Based on the results of in vitro studies, it is reasonable to suppose that insulin therapy in type 2 diabetes is associated with an increased risk of cancer." (PMID 23209929, 2012). "On the other hand, there have been reports of improved insulin sensitivity in type 2 diabetes and a reduced risk of cardiovascular diseases with improved adiponectin levels." (PMID 23304216, 2012). "This metabolic threshold is crossed in Type 2 diabetes and results in β-cell dysfunction including the loss of glucose stimulated insulin secretion." (PMID 23300881, 2012). "In conclusion, we clearly demonstrate that the initiation of insulin therapy is associated with an acute, but transient, rise in myocardial lipid content in patients with long standing type 2 diabetes and poor metabolic control." (PMID 23226508, 2012). "The main limitations of insulin therapy in type 2 diabetes are weight gain and the risk of hypoglycemia; the latter has also been associated with increased cardiovascular mortality." (PMID 23209929, 2012). "In type 2 diabetes progressive insulin deficiency and duration of insulin therapy increase the risk of hypoglycemia as in type 1 diabetes, and the risk of hypoglycemia is highest in those with type 2 diabetes who have received insulin for more than 10 years." (PMID 23497433, 2012). "A non-synonymous polymorphism in the Slc30a8 gene encoding the insulin granule Zn2+ transporter Slc30a8 (ZnT8) has been associated with the risk of developing type 2 diabetes." (PMID 23056475, 2012). "Pancreatic β-cell dysfunction is a diagnostic criterion of Type 2 diabetes and includes defects in glucose transport and insulin secretion." (PMID 23300881, 2012). "Prudentially, metformin should be associated with insulin in type 2 diabetes, unless contraindicated." (PMID 23209929, 2012).